TREM2 (triggering receptor expressed on myeloid cells 2)
Diseases named in the same sentence as TREM2 in open-access papers (continued):
Sharing a sentence is not in itself a finding about the gene and the disease.
tumor (continued). "Similar to the scaffold, liver and primary tumor, C1QA, C1QB, and TREM2 marked only one subpopulation of monocytes (CQ-Monocytes) in human PBMCs." (PMID 33782087, 2021). "Based on TCGA analysis for the downregulated genes from our RNA-Seq data, high gene signature comprising of TREM2, CATSPER1, NPL, and PRAM1 in tumor-infiltrating PMN-MDSC predicted poor OS rates in COAD patients." (PMID 33312958, 2020). "Reduced tumor TREM2 expression was correlated with poor prognosis of HCC patients, and with aggressive pathological features (BCLC stage, tumor size, tumor encapsulation, vascular invasion, and tumor differentiation)." (PMID 30683932, 2019). "Clinicopathological analysis revealed that TREM2 downregulation was significantly correlated with aggressive pathological features, like BCLC stage, tumor size, tumor encapsulation, vascular invasion and tumor differentiation." (PMID 30683932, 2019). "3LL cells mixed with TREM-2+DCs and TREM-2−DCs (ratio = 5:1) were injected subcutaneously and the tumor diameters evaluated 28 days later." (PMID 27102437, 2016). "Taken together, these results speculated that although TREM-2 had a protective role in maintaining homeostasis of osteoclast and CNS development, it might be more likely to be involved in the negative modulation of immune function and facilitate immune evasion in the tumor bearing host." (PMID 27102437, 2016). "Thus, targeted therapy with anti-TREM2 antibodies can induce immune responses, inhibit tumor progression, and enhance ICB efficacy, making TREM2 a potential target for cancer immunotherapy." (PMID 40670983, 2025). "Although TREM2 is associated with immunosuppression and poor prognosis in the RCC tumor microenvironment, the depletion of tumor-associated macrophages by PY314 did not significantly translate into clinical anti-tumor benefits." (PMID 40242752, 2025). "AR+/TREM2+/SPP1+ TAM fraction; TAM–tumor proximity scores; APOE–TREM2 pathway activity." (PMID 41488638, 2025). "Importantly, when adding anti-TREM2 to PD1/LAG3 blockade, mice with a decrease in tumor volume had tumors less infiltrated by immunosuppressive macrophages, while still enriched in TCF+ PD1+ T cells and DCs compared to non responders." (PMID 40027748, 2025). "Therefore, further investigations are warranted to explore the role of TREM2 in HCC and its impact on the tumor microenvironment." (PMID 39838454, 2025). "These are tissue-resident, rather than tumour-associated, C1Q+ macrophages because state #45 cells significantly more highly express FOLR2, rather than TREM2, relative to state #40." (PMID 39748128, 2025). "Interestingly, PPARγ expression aligns with descriptions of SPP1+ macrophages as foamy cells, a feature reported in lung cancer TAMs expressing both TREM2 and SPP1, where they have been shown to promote cholesterol efflux, fuelling tumour cell metabolism." (PMID 40395129, 2025). "Across these specimens, TREM2 predominantly localized to areas with CD163+ macrophages rather than cytokeratin (PanCK)-positive tumor cells." (PMID 39744236, 2025). "Additionally, transcriptome sequencing (ST-seq) analysis revealed a co-expression pattern of TREM2 and TREM1 in the tumor-infiltrating myeloid cells of high-grade clear cell renal cell carcinoma (HG ccRCC)." (PMID 40242752, 2025). "Furthermore, TREM2+ Macrophages attracted exhausted CD8+ T cells through chemotaxis facilitated by CXCL12, thereby accelerating T cell exhaustion in tumor tissues." (PMID 38948071, 2024). "The proportion of tumor-infiltrating CD45.2+ macrophages was notably increased in the group injected with WT monocytes compared to the group injected with TREM2 KO monocytes, suggesting that TREM2 promotes the recruitment of circulating monocytes to the TME." (PMID 39135069, 2024). "High expression of ANXA2, TREM2, TTC39A, and GDF15 may lead to a more suppressive tumor microenvironment and enhanced immune escape, thereby reducing the efficacy of immunotherapy." (PMID 39697329, 2024).
tumor (continued). "Cellchat software revealed robust interactions specifically between TREM2+ Macrophages and C3_CD8+ Tex in tumor tissues, rather than in the border and normal tissues." (PMID 38948071, 2024). "Sensitive, sonic hedgehog (Shh) pathway-driven BCC epithelium arises through the ability to recruit and instruct TREM2 + VCAM1+ myeloid cells into a self-propagating phenotype that allows mutual proliferation and tumor growth with a dearth of effector lymphocytes present in the local environment." (PMID 39289380, 2024). "Similarly to ECM-myCAF, IFNαβ-myCAF and TGFβ-myCAF clusters, TREM2+ TAM and SPP1+ TAM cells were detected within the tumor bed." (PMID 38561380, 2024). "In patients with non-small cell lung cancer, TREM2 acts as a negative immunoregulatory molecule, and its expression is positively correlated with tumor progression." (PMID 39113887, 2024). "Furthermore, we conducted flow cytometry on tumor and adjacent non-tumor tissues from HCC patients, and the results showed that the density of TREM2+ subpopulation was higher in tumor tissues." (PMID 38948071, 2024). "Compared to TREM2-TAM, TREM2 + TAMs secrete lower levels of CXCL9 but higher levels of galactagogue lectin-1, which promotes PD-L1 overexpression in vascular endothelial cells, impedes CD8 + T cell recruitment, and fosters tumor growth." (PMID 39068459, 2024). "Additionally, scatter plots revealed a positive correlation between TREM2 and ANXA2 with both the StromalScore and ImmuneScore, suggesting their roles in modulating the tumor microenvironment." (PMID 39697329, 2024). "Subsequent research showed that the uptake of tumour debris induced the TREM2 gene program in mouse monocyte-derived macrophages (including Trem2, Lpl, Cd274, and Apoe), while non-phagocytic cells are immunogenic." (PMID 39430099, 2024). "Furthermore, TREM2 influences key signaling pathways such as the Wnt/β-catenin and PI3K/Akt pathways, which are crucial in oncogenesis and tumor progression." (PMID 39697329, 2024). "Moreover, TREM2 plays an immunosuppressive role in tumor microenvironment (TME), which can negatively regulate anti-tumor immune response and assist tumor cell immune escape." (PMID 38725629, 2024). "Ablation of Trem2 gene may suppress Mreg, exhausted CD8+ T cells and thus, the overall tumor growth." (PMID 37335084, 2023). "In particular, C3aR1, C5aR1, MMP-14, THBS1, and TREM2 were abnormally highly expressed in orthotopic tumor tissue but were not expressed in lymph node metastasis-negative tissues." (PMID 37744272, 2023). "Trem2+ MHC-IIlow TAMs are immunosuppressive and promote tumor survival and growth, and likewise Trem2+ MHC-IIlow uterine macrophages may also be immunosuppressive and promote fetal survival and growth." (PMID 37901247, 2023). "SCAMs represent a unique tumor-specific TREM2+ population defined by VCAM1 surface expression that is not found in normal homeostatic skin or during wound healing." (PMID 37164949, 2023). "The tumor growth curve showed a trend consistent with the longitudinal bioluminescence assay, indicating significant early-stage inhibition of tumor growth in the BsAb-treated group compared with that in the PBS-, PD-1 scFv- and TREM2 scFv-treated groups." (PMID 37563723, 2023). "However, previous studies suggest that several of the identified proteins are potent stimulators of tumor cell proliferation or invasiveness, including SPARCL1, IGF-BP2, osteopontin, FAM3C, TREM2, CD166, prosaposin, and kininogen-1/bradykinin." (PMID 35659255, 2022). "Through targeting of TREM2 with an anti-TREM2 monoclonal antibody, they could show a depletion of TAM in the TME and an increase in anti-tumor activity." (PMID 35804950, 2022). "Several proteins that are involved in tumor growth were present in glioblastoma cyst fluid (for references, see “Discussion” section): SPARCL1, IGF-BP2, osteopontin, FAM3C, TREM2, CD166, and prosaposin promote tumor cell proliferation, migration, and invasiveness." (PMID 35659255, 2022).
tumor (continued). "Both studies attribute the reduction in tumor growth to the lack of TREM2 expression on the immune cells and thus a reduced ability of the immune cells to create an immunosuppressive environment." (PMID 36119485, 2022). "C4 TAMs (964 cells in residual tumor) express SPP1, TREM2 and APOE." (PMID 35784460, 2022). "Thus, the function of TREM2 in human HCC, especially in tumor immune responses, warrants further investigation." (PMID 35359989, 2022). "To rule out the tumor itself as a possible supply of sTREM-2, we examined Trem2 message levels in 4T1 tumor cells." (PMID 35223446, 2021). "The data from Kaplan–Meier curves showed that HCC patients with negative TREM2 expression in their tumor tissues had shorter survival and increased recurrence than those with positive expression." (PMID 30683932, 2019). "The result showed that TREM2 level was obviously downregulated in tumor tissues compared with that in the non-tumor tissues at mRNA and protein levels." (PMID 30683932, 2019). "The semi-quantitative scores analysis of immunohistochemical (IHC) staining implied that TREM2 was markedly downregulated in tumor compared with that in matched non-tumor tissues." (PMID 30683932, 2019). "Fourth, we carried out chromatin immunoprecipitation (ChIP) assay and found that histone acetylation of TREM2 gene was not obviously altered in tumor tissues compared with that in non-tumor tissues." (PMID 30683932, 2019). "Most of the bacteria (for instance B. xylanisolvens, Paraprevotella clara, Prevotella timonensis) were positively relating with anti-inflammatory/tumor markers (e.g. Trem-2, MR, arginase-1, TNF-α) and negatively correlating with pro-inflammatory/tumor markers (e.g. IL-12, IL-6 and iNOS)." (PMID 28970547, 2017). "The number of TREM-2+CD11c+DCs and the MFI of TREM-2 expression on DCs from lung increased after tumor bearing while these two indexes of DCs had no alteration in the spleen and blood of tumor-bearing mice compared to that of normal mice." (PMID 27102437, 2016). "In some models, TREM2+ macrophages may coexist with other immunosuppressive populations, suggesting that TREM2 inhibition alone may not fully remodel the tumor microenvironment, thus requiring combination therapies." (PMID 40821795, 2025). "Importantly, TREM2 and CXCR2 directly promote the protumor functions of TAMs, and the inhibition of their expression and activity has been shown to suppress tumor growth and enhance the efficacy of tumor immune therapy." (PMID 41440012, 2025). "TREM2 is expressed on CSF1R+ TAMs and modulated by CSF1, suggesting that dual inhibition of CSF1R and TREM2 may further potentiate macrophage repolarization and tumor immune surveillance." (PMID 40330466, 2025). "Notably, within these cell clusters, TREM2 shows specifically high expression in macrophages, rather than tumor cells." (PMID 39744236, 2025). "This strategy could enhance the efficacy of immunotherapies by increasing tumor immunogenicity, thereby improving responsiveness to treatments such as immune checkpoint inhibitors and macrophage-targeted therapies, including CSF1R and TREM2 inhibitors." (PMID 40330466, 2025). "Moreover, Tumor IMmune Estimation Resource (TIMER) analysis of TCGA-LIHC dataset revealed a negative correlation between the expression of TREM2 and TGFB1 and the infiltration levels of naive CD8+ T cells." (PMID 39838454, 2025). "However, in a peripheral tumor model, subcutaneous injection of GL261 or EO771 cells led to slower tumor growth in Trem2−/− mice, accompanied by a shift in the tumor microenvironment toward a pro-inflammatory state, again suggesting that TREM2 promotes tumor growth in peripheral tumors." (PMID 40242752, 2025).
tumor (continued). "“T cell” neighborhoods enriched with effector T cells and mature macrophages that lacked tumor epithelium lie immediately adjacent to drug-sensitive proliferating BCC surrounded by TREM2 + VCAM1+ myeloid cells or resistant BIT tumors surrounded by lymphocyte-poor TREM1+ myeloid-driven inflammation." (PMID 39289380, 2024). "Interestingly, we were unable to find any correlation with our set of inflamma-miRNAs either for Gfap or Trem2, though it was validated for miR-34a impact, a known tumor suppressor not assessed in the present study." (PMID 39273422, 2024). "Moreover, TREM2 inhibited macrophage-expressed antigen-presenting molecules MHC-I/II and the coactivators CD80/CD86, suggesting that TREM2 also affects T cell-mediated anti-tumor immune response." (PMID 39135069, 2024). "Notably, TREM2 can also act as a β-catenin regulator by promoting the proteasomal degradation of β-catenin in the cytoplasm and negatively regulating the Wnt/β-catenin signaling pathway, which in turn inhibits CRC tumor progression in vivo and in vitro." (PMID 38725629, 2024). "Additionally, patients with high TREM2 expression have lower MSI scores, suggesting these genes may contribute to immune evasion mechanisms in the tumor environment." (PMID 39697329, 2024). "In addition, TREM2+ LAMs can also interact with Treg cells via the CCL20/CXCL9/CXCL10/CXCL12-CXCR3 axis, recruiting suppressor Treg cells, inhibiting the function of effector T cells, and promoting tumor microenvironment remodeling." (PMID 38725629, 2024). "Further experiments showed that the lack of TREM2 can inhibit the growth of tumor-infiltrating macrophages, reduce the number of CX3CR1+ and MRC1+ macrophage subgroups, and enhance the reactivity of CD8+ T cells to anti-PD-L1, thereby remodeling the TME in mouse bone marrow metastasis." (PMID 37858183, 2023). "In addition, TREM2+ LAM-like cells were predominantly enriched in tumor compared with adjacent nontumor tissues, although displayed a comparable expression level of TREM2." (PMID 35359989, 2022). "The accumulation of TREM2+ cells was confirmed in virtually all tumor samples, while TREM2 staining was scant or absent in adjacent liver tissues, suggesting that TREM2 may be a particularly attractive therapeutic target." (PMID 35359989, 2022). "We detected no Trem2 mRNA in 4T1 tumor cells when compared to a macrophage line." (PMID 35223446, 2021). "Additionally, RNA sequencing of CRC cells with TRIP13 knockdown identified COL6A3, TREM2, SHC3, and KLK7 as downstream targets that may have functional relevance in TRIP13‐mediated tumor growth and metastasis." (PMID 33037736, 2020). "We next examined whether TREM-2 mRNA and miR-34a were expressed in three human cholangiocyte cell lines: a primary culture of normal human cholangiocytes (NHCs), as well as non-tumor immortalized human cholangiocytes (H69) with or without experimental overexpression of miR-506 (PBC human model)." (PMID 40801570, 2025). "Additionally, it would be interesting to investigate the potential interactions between GZMK, TREM2, and OR4D10 and other immune-related genes in the tumor microenvironment, which could provide new insights into the complex interplay between cancer cells and the immune system." (PMID 40332815, 2025). "Interestingly, the tumor microenvironment of human HCCs is also abundantly infiltrated by TREM2+-macrophages displaying a pro-angiogenic and immunosuppressive phenotype, while HCC patients with an expanded fraction of TREM2+-macrophages show poor survival rate." (PMID 36691794, 2023). "Moreover, TREM2 modulation by genetic ablation or monoclonal antibodies can remodel the myeloid cell immunosuppression within the TME, restrict tumor growth, and further improve immunotherapies such as anti-PD-1 therapy and NK cell-based therapy in mouse models with different tumor types." (PMID 37771596, 2023).
tumor (continued). "Moreover, mice lacking Trem2 display exacerbated liver damage and inflammation in the context of toxin-induced hepatocellular injuries and even an elevated tumor burden in the early phases of liver tumorigenesis, suggesting that TREM2 plays a protective role in hepatocarcinogenesis." (PMID 35359989, 2022). "scRNA-seq landscape in responsive and non-responsive HCC patients treated with anti-PD-1 therapy reveals a significant accumulation of TREM2+ macrophages in non-responsive samples, while TCR+ macrophages exhibit tumor-killing capacity." (PMID 40051497, 2025). "Importantly, unlike the TREM2 myeloid cell signature, the 16-gene BIT-associated TREM1 myeloid signature was specifically enriched in BIT regions spatially, reinforcing the spatial association between BIT tumor epithelium and the specialized TREM1 myeloid cell-associated inflammatory environment." (PMID 39289380, 2024). "To explore the complexity of TREM2+ cells in the tumor microenvironment (TME), we first characterized the human HCC single-cell transcriptome atlas of tumor and corresponding nontumor samples from 14 HCC patients (Discovery cohort)." (PMID 35359989, 2022). "In ICIs non-responders, macrophages overexpressing TREM2 show a unique gene expression pattern and overexpress key genes of the complement system (C3, C1QA, C1QB, and C1QC) and M2 polarization genes, which block the anti-tumor activity of ICIs, leading to ICIs resistance." (PMID 38725629, 2024).